SNHG14 (small nucleolar RNA host gene 14)
Diseases named in the same sentence as SNHG14 in open-access papers (continued):
Sharing a sentence is not in itself a finding about the gene and the disease.
glioma (continued). "The relative expression levels of SNHG14 were measured in 29 paired glioma tissues and their corresponding NATs using qRT-PCR and were normalized to GAPDH." (PMID 29552296, 2018). "Next, we identified the tumour suppressive role of SNHG14 in glioma progression based on functional experiments." (PMID 29552296, 2018). "In this study, we found that SNHG14 was downregulated in glioma cells and tissues, and its overexpression significantly inhibited cell proliferation and invasion, suggesting that SNHG14 acts as a tumour suppressor in glioma progression." (PMID 29552296, 2018). "Therefore, considering the lin28a/SNHG14/IRF6 axis as a target provides novel insight for the treatment of glioma." (PMID 34178684, 2021). "Since our results revealed the oncogenic nature of Lin28A and SNHG14 in glioma cells and the decrease in SNHG14 in the sh-Lin28A cells as compared to that in the sh-Lin28A-NC group, we speculated a positive correlation between SNHG14 and Lin28A." (PMID 32527996, 2020). "Thus, Lin28A facilitated aerobic glycolysis by stabilizing SNHG14, thereby enhancing cell proliferation and impairing apoptosis in glioma cells." (PMID 32527996, 2020). "In addition, SNHG14 was reported as inhibitor in malignant glioma by suppressing cell growth, invasion, and promoting apoptosis in glioma cell lines via targeting miR-92a-3p." (PMID 30546117, 2019). "Finally, mechanistic investigations revealed that SNHG14 inhibited glioma progression by acting as a sponge for miR-92a-3p." (PMID 29552296, 2018). "Collectively, the results showed that SNHG14 was downregulated in glioma." (PMID 29552296, 2018). "Taken together, these results suggest that SNHG14 and miR-92a-3p may be potential therapeutic targets for glioma therapy." (PMID 29552296, 2018). "Moreover, miR-92a-3p overexpression significantly reversed the tumour suppression effects induced by SNHG14 overexpression in glioma." (PMID 29552296, 2018). "The relative expression levels of SNHG14 in 29 gliomas were also compared with those in 18 NBTs." (PMID 29552296, 2018). "SNHG14 expression was significantly lower in glioma tissues than that in NBTs (p < 0.001)." (PMID 29552296, 2018). "In summary, decreased expression of SNHG14 was observed in glioma patients." (PMID 29552296, 2018). "The relative expression levels of SNHG14 in glioma cell lines were also measured." (PMID 29552296, 2018). "SNHG14 was found to be downregulated in human glioma tissues and cell lines." (PMID 29552296, 2018). "This suggests that stabilizing SNHG14 could target aberrant metabolism in glioma cells." (PMID 33126510, 2020). "However, very little is known about the effect of SNHG14 on glycolysis in glioma." (PMID 32527996, 2020). "Taken together, these data indicated that miR-92a-3p could directly bind to SNHG14 in glioma cells." (PMID 29552296, 2018). "Moreover, mechanistic investigations showed that miR-92a-3p could reverse the tumour suppressive effects induced by SNHG14 in glioma, indicating that SNHG14 may act as an endogenous sponge that competes for binding to miR-92a-3p." (PMID 29552296, 2018). "Quantitative real-time polymerase chain reaction and western blotting showed that Lin28A and SNHG14 were overexpressed and IRF6 was downregulated in glioma." (PMID 32527996, 2020). "Taken together, our data revealed that the Lin28A/SNHG14/IRF6 axis is crucial for reprogramming glucose metabolism and stimulating tumorigenesis in glioma cells." (PMID 32527996, 2020). "This study reveals the oncogenic nature of Lin28A and SNHG14, while IRF6 functions as a tumor suppressor in glioma." (PMID 32527996, 2020). "Therefore, we speculated that Lin28A might regulate SNHG14 in glioma cells." (PMID 32527996, 2020). "Therefore, the lin28A/SNHG14/IRF6 axis is crucial for reprogramming glucose metabolism and promoting tumor development in glioma cells." (PMID 38967893, 2024).
glioma (continued). "Lin28a elevated the expression and stability of SNHG14, while deletion of SNHG14 increased the expression of IRF6, which inhibited the transcription of PKM2 and GLUT1 and thus impaired glycolysis and proliferation of glioma cells and induced apoptosis." (PMID 34178684, 2021). "Single or combination therapy targeting Lin28A, SNHG14, and IRF6 has the potential in clinical settings and may help develop new therapeutic strategies for treating glioma." (PMID 32527996, 2020). "We hypothesized that interactions within the Lin28A/SNHG14/IRF6 axis may be responsible for reprogramming glucose metabolism, thereby stimulating the development and progression of glioma." (PMID 32527996, 2020). "Phenotypes induced by depleting SNHG14 (decreased the expression of PKM2 and GLUT1; inhibition of glycolysis and glycolytic capacity, lactate production and glucose uptake; suppression of proliferation; enhanced apoptosis) could be reversed by silencing IRF6 in glioma cells." (PMID 32527996, 2020).
hepatocellular carcinoma (9 papers, 2020 to 2026). A malignant tumor that arises from hepatocytes. "Moreover, the aberrant expressions of some lncRNAs mentioned in this review have also been shown to underlie the onset and pathogenesis of other cancers, such as MALAT1 and SNHG14, which seem to be possible diagnostic and prognostic therapeutic biomarkers in colorectal and hepatocellular cancer." (PMID 36558998, 2022). "SNHG14 (Small Nucleolar RNA Host Gene 14): SNHG14, a lncRNA, has been implicated in various cancer types, including CRC and hepatocellular carcinoma (HCC), demonstrating a significant impact on cancer progression." (PMID 37760852, 2023). "Furthermore, SNHG14 can upregulate PABPC1 via H3K27 acetylation, regulating the PTEN signalling pathway in hepatocellular carcinoma cells while promoting cell proliferation and angiogenesis." (PMID 40521987, 2025).
cerebral infarction (7 papers, 2017 to 2021). An ischemic condition of the brain, producing a persistent focal neurological deficit in the area of distribution of the cerebral arteries. "Further, SNHG14 was involve in regulation of microglia activation in cerebral infarction." (PMID 30546117, 2019). "Moreover, SNHG14 participated in promoting microglia activation by modulation miR-145–5p/PLA2G4A in cerebral infarction." (PMID 30546117, 2019). "Additionally, SNHG14 knockdown suppresses the activation of microglia cells which release inflammatory cytokines following ischemic stroke, in so doing conferring protection against cerebral infarction." (PMID 31660971, 2019). "SNHG14 promoted the microglia cells (MCs) classical activation by the inhibition of miR-145-5p, which resulted in the high levels of TNF-α and NO in MCs during cerebral infarction." (PMID 28915705, 2017).
clear cell renal cell carcinoma (7 papers, 2018 to 2021). "Of interest, SNHG14 up-regulation in clear cell renal cell carcinoma cells could stimulate cell to migrate and invade." (PMID 33482820, 2021). "Moreover, SNHG14, as a key lncRNA, facilitated the migration and invasion of clear cell renal cell carcinoma via sponging miR-203 and accelerate Neural Wiskott-Aldrich syndrome protein." (PMID 33176720, 2020).
diffuse large B-cell lymphoma (7 papers, 2019 to 2024). "Small nucleolar RNA host gene 14 (SNHG14), which interacts with miR-5590-3p, is upregulated in diffuse large B-cell lymphoma (DLBCL) cells, where it triggers CD8+ T cell apoptosis and enhances DLBCL growth by activating the PD-L1/PD-1 immune checkpoint." (PMID 35659268, 2022). "For example, in diffuse large B-cell lymphoma, the lncRNA SNHG14 upregulates the mRNA ZEB1 by competitively binding to miR-5590-3p, and ZEB1 positively activates SNHG14 and PD-L1, thereby promoting immune escape of tumor cells." (PMID 38485995, 2024). "In diffuse large B-cell lymphoma (DLBCL), SNHG14 can stimulate crosstalk between CD8+ T cells and DLBCL cells and induce CD8+ T cells by directly targeting the immune checkpoints PD-1/PD-L1." (PMID 34631703, 2021).
ischemic stroke (6 papers, 2018 to 2022). A stroke disorder caused by obstruction of blood flow to the brain, due to thrombotic (local blood clot formation) or embolic (due to a blood clot or other material traveling from another site) event. "SNHG14 was uncovered to be highly expressed in ischemic stroke, and the inhibition of SNHG14 mitigated neuron inflammatory damage." (PMID 33071725, 2020). "Other lncRNAs, such as ANRIL, SNHG14, TUG1, and MEG3, were also found to affect neuronal apoptosis, inflammation and angiogenesis during ischemic stroke." (PMID 35677353, 2022).
osteosarcoma (6 papers, 2020 to 2024). A usually aggressive malignant bone-forming mesenchymal neoplasm, predominantly affecting adolescents and young adults. "In osteosarcoma cells, Hou and co‐workers reported that the lncRNA small nucleolar RNA host gene 14 (SNHG14) accelerated tumour progression by targeting miR‐433‐3p and FBXO22 in osteosarcoma." (PMID 39153212, 2024). "Token together, SNHG14 enhanced osteosarcoma progression through modulation of miR-433-3p/FBXO22 pathway." (PMID 32793396, 2020). "Recent studies indicated that SNHG14 functioned as a tumor promoter by sponging different miRNAs in a series of cancers, such as retinoblastoma, pancreatic ductal adenocarcinoma, and osteosarcoma." (PMID 33071725, 2020). "The expression of SNHG14 is up-regulated in various cancers, such as osteosarcoma, pancreatic ductal adenocarcinoma, and lung adenocarcinoma." (PMID 32912324, 2020). "Downregulation of FBXO22 or SNHG14 inhibited proliferation, motility of osteosarcoma cells, but stimulated apoptosis." (PMID 32793396, 2020). "Small nucleolus RNA host gene 14 (SNHG14), one long noncoding RNA, was reported to act as a competing endogenous RNA (ceRNA) to decoy miR-433-3p and subsequently increase FBXO22 expression in osteosarcoma cells." (PMID 32793396, 2020).
non-small cell lung carcinoma (5 papers, 2020 to 2022). A group of at least three distinct histological types of lung cancer, including non-small cell squamous cell carcinoma, adenocarcinoma, and large cell carcinoma. "It is reported that lncRNA SNHG14 involved in procession of many cancers, such as pancreatic ductal adenocarcinoma, cervical cancer, renal cell carcinoma and non-small cell lung cancer, and so on 21-23." (PMID 34234865, 2021). "SNHG14 participates in the cell proliferation, invasion and migration of non-small cell lung cancer cells by regulating miR-206/G6PD." (PMID 32912324, 2020). "In addition to its function in tumorigenesis and progression, SNHG14 was found to function as a competing endogenous RNA for microRNAs-382-5p (miR-382-5p) to regulate SPIN1 expression in non-small cell lung cancer." (PMID 34631721, 2021).
ovarian carcinoma (5 papers, 2019 to 2025). A malignant neoplasm originating from the surface ovarian epithelium. "SNHG14 is overexpressed in ovarian cancer tissues and is negatively associated with the overall survival of patients." (PMID 41200835, 2025). "For example, the level of lncRNA small nucleolar RNA host gene 14 (SNHG14) is significantly increased in ovarian cancer tissues, and the inhibition of SNHG14 significantly inhibits the migration and invasion of cells." (PMID 34432955, 2021). "Among these LncRNAs, MALAT1 and SNHG14 have been demonstrated to function as oncogenes in ovarian cancer." (PMID 31794425, 2019). "Dual-luciferase assay indicated that SNHG14 could directly bind to miR-125a-5p, and overexpression of miR-125a-5p reversed the effect of promoting tumor of SNHG14 on ovarian cancer cells." (PMID 34631721, 2021). "SNHG14 was also found to promote ovarian cancer metastasis by regulating DGCR8 expression." (PMID 34631721, 2021).
pancreatic cancer (5 papers, 2019 to 2026). "Collectively, SNHG14 shows its role in the initiation, progression, and drug resistance, suggesting its potential role in tumor treatment of pancreatic cancer." (PMID 34631721, 2021). "SNHG14 overexpression enhanced cell proliferative, growth and invasive abilities, and suppressed apoptotic rates and caspase‐3 activity in pancreatic cancer cells, while SNHG14 knockdown exerted opposite effects." (PMID 31513352, 2019). "Localization of SNHG14 should be determined by immunohistochemistry to confirm the up‐regulation of SNGH14 in pancreatic cancer tissues." (PMID 31513352, 2019). "In conclusion, this study identified the interaction network of SNHG14 and miR‐613 in pancreatic cancer." (PMID 31513352, 2019). "In the current investigations, the role of the lncRNA small nucleolar RNA host gene 14 (SNHG14) in pancreatic cancer was explored and found that up‐regulation of SNHG14 was detected in tissues and cell lines of the pancreatic cancer." (PMID 31513352, 2019). "The link between SNHG14 expression and the overall survival of pancreatic cancer patients should be examined to further confirm the prognostic potential of SNHG14 in pancreatic cancer." (PMID 31513352, 2019). "The qRT‐PCR results detected the up‐regulation of SNHG14 in pancreatic cancer tissues, with the relatively higher SNHG14 expression level than that in adjacent non‐tumour tissues." (PMID 31513352, 2019). "Low or high expression of SNHG14 in cancerous tissues from pancreatic cancer patients was classified based on the median values." (PMID 31513352, 2019). "Collectively, our results suggest that SNHG14 potentiates pancreatic cancer progression through modulation of annexin A2 expression via acting as a competing endogenous RNA for miR‐613." (PMID 31513352, 2019). "This study aimed to determine long non‐coding RNA (lncRNA) small nucleolar RNA host gene 14 (SNHG14) expression in pancreatic cancer and to explore the potential molecular actions of SNHG14 in mediating pancreatic cancer progression." (PMID 31513352, 2019). "Here, functional assays showed that up‐regulation of SNHG14 promoted proliferative, growth, and invasive abilities, and suppressed cell apoptosis in pancreatic cancer cells, while silencing of SNHG14 exerted the opposite effects." (PMID 31513352, 2019). "Some studies have reported that SNHG14 expression was significantly higher in pancreatic cancer cells compared with that in normal cell lines, and upregulated this lncRNA enhanced cell proliferation and invasion through regulating E-cadherin expression via binding on promoters of EZH2." (PMID 34631721, 2021). "High SNHG14 expression in the cancerous tissues showed a positive correlation with poorer tumour differentiation, more advanced TNM stage and nodal metastasis, but had no associated with age, sex and tumour size in patients with pancreatic cancer." (PMID 31513352, 2019). "SNHG14 expression was up‐regulated in cancerous tissues from pancreatic cancer patients." (PMID 31513352, 2019). "Furthermore, miR‐613 was experimentally confirmed as a target of SNHG14, and SNHG14 down‐regulated miR‐613 expression in pancreatic cancer cells." (PMID 31513352, 2019). "Similarly, up‐regulation of SNHG14 was also detected in the pancreatic cancer cell lines (BXPC3, CFPAC‐1 L3.6pl and Panc‐1) when compared with that in the normal cell line (HPDE6C7)." (PMID 31513352, 2019). "Our studies suggested that SNHG14 may be a prospective target for the management of pancreatic cancer." (PMID 31513352, 2019). "In addition, the miR‐613 expression level was lower and the ANXA2 mRNA expression level was higher in the pancreatic cancer tissues with high expression of SNHG14 than those with low expression of SNHG14." (PMID 31513352, 2019).
pancreatic cancer (continued). "Our current findings suggest that SNHG14 potentiates pancreatic cancer progression through modulation of annexin A2 expression via acting as a competing endogenous RNA for miR‐613, and that the SNHG14‐miR‐613‐ANXA2 axis may represent a key signalling pathway for pancreatic cancer progression." (PMID 31513352, 2019). "Furthermore, some researchers discovered that highly expressed SNHG14 was positively correlated with large tumor size, advanced TNM stage, distant metastasis and poor tumor differentiation in bladder cancer, NSCLC, HCC, prostate cancer, retinoblastoma, pancreatic cancer, and cervical cancer." (PMID 34631721, 2021).
pancreatic ductal adenocarcinoma (5 papers, 2019 to 2021). An infiltrating adenocarcinoma that arises from the epithelial cells of the pancreas. "Besides, lncRNA SNHG14 also down-regulates miR-101 to facilitate cell progression in pancreatic ductal adenocarcinoma, while we discovered that lncRNA SNHG14 performs a likewise role in ALI." (PMID 31660971, 2019).
Angelman syndrome (4 papers, 2018 to 2022). A neurogenetic disorder characterized by severe intellectual deficit and distinct facial dysmorphic features. "Of note, among the top transcripts upregulated by SNI in the mPFC of SNI female mice, Snhg14 encodes a long non-coding RNA that regulates the expression of ubiquitin protein ligase E3A (Ube3a), which is known to critically implicate in the social interaction dysfunction in Angelman’s syndrome." (PMID 35663269, 2022). "Thus, overexpression of SNHG14 and silencing of UBE3A expression were associated with neuronal differentiation in Angelman syndrome model." (PMID 30546117, 2019). "Small nucleolar RNA host gene 14 (SNHG14) is located within the Prader-Willi critical region and extends in antisense into the region of the ubiquitin protein ligase E3A (UBE3A) gene, whose deficiency in brain cells in children causes neurogenetic disorders, such as Angelman syndrome." (PMID 29552296, 2018). "As its locus overlaps with UBE3A gene and promoter, thus SNHG14 prevents UBE3A expression and leads to neurogenetic disorders, such as Angelman syndrome." (PMID 30546117, 2019).
bladder cancer (4 papers, 2020 to 2022). "Upregulation of SNHG14 promoted the proliferation and cell cycle progression in bladder cancer by regulating miRNA-150-5p." (PMID 36120583, 2022). "The expression level of SNHG14 in bladder cancer cell lines (T24, 5637, UMUC-3, and EJ) was higher than in normal bladder epithelial cells SV-HCV-1." (PMID 34631721, 2021). "Moreover, further expression analyses suggested a downregulation of CKMT2-AS1, SGMS1-AS1, and SNHG14 (all p < 0.05) in bladder cancer." (PMID 36120583, 2022). "By constructing an mRNA–miRNA–lncRNA network, we identified an lncRNA SNHG14/miR-20a-5p/CASP8 regulatory axis, which may play a vital role in the development of bladder cancer." (PMID 36120583, 2022). "To date, there have been no reports on functions of SNHG14, HCG18, and MAGI2-AS3 in melanoma, but they constitute a precisely regulated ceRNA network in various solid tumors such as colon cancer, bladder cancer, liver cancer, etc., and regulate the malignant behavior of tumor cells." (PMID 33194692, 2020).
cardiac hypertrophy (4 papers, 2020 to 2026). "The report also suggested that lncRNA SNHG14 (small nucleolar RNA host gene 14) was validated to sponge both miR-322-5p and miR-384-5p to elevate PCDH17 levels in vivo and in vitro cardiac hypertrophy models." (PMID 37342178, 2022). "Research indicates that SP1-induced SNHG14 aggravates cardiac hypertrophy by sponging miR-322-5p and miR-384-5p to upregulate protocadherin 17 (PCDH17), making SNHG14 a potential biomarker for cardiac hypertrophy." (PMID 41602333, 2026).
cervical cancer (4 papers, 2019 to 2021). A primary or metastatic malignant neoplasm involving the cervix. "Other studies on cervical cancer, prostate cancer, osteosarcoma, endometrial cancer, retinoblastoma, clear cell renal cell carcinoma, diffuse large B cell lymphoma, and acute myeloid leukemia indicated a tumor promoter role for SNHG14 through complex molecular mechanisms." (PMID 34631721, 2021).